CXCL10 (C-X-C motif chemokine ligand 10)
Diseases named in the same sentence as CXCL10 in open-access papers (continued):
Sharing a sentence is not in itself a finding about the gene and the disease.
Obesity (continued). "Further investigations on primary monocyte subsets in larger cohorts in correlation with adipose tissue-infiltrating macrophages are needed to unravel the impact of monocytic CXCL10/CX3CR1/MIF signaling on obesity-related systemic inflammation and its concomitant diseases." (PMID 38175171, 2024). "The decreased expression of downregulated DEGs enriched in Ca2+ metabolism, including CXCL10, CXCL13, and PDE1C, as identified in this study could play a role in obesity and its associated complications by lowering Ca2+ levels." (PMID 39609876, 2024). "Clostridium_sensu_stricto_1, neuromedin N, enkephalin L, Pck1, 5-hydroxy-L-tryptophan, Cxcl10 and cinnamyl alcohol may be novel biomarkers in the small intestine for obesity/obesity resistance." (PMID 36209126, 2022). "Thus, FFC-fed CXCL10−/− mice have similar hepatic steatosis as compared to WT mice on the same obesity-inducing diet, but display reduced hepatic inflammatory infiltrates." (PMID 27349927, 2016). "Other chemokines include but not limited to CCL2 (MCP-1), CCL3 (MIP-1α), CCL4 (MIP-1β), CCL19, CXCL1, CXCL8 or IL-8, CXCL10, and CXCL12 also play an important role in obesity and cancer immunotherapy." (PMID 40863244, 2025). "We studied the distribution of the CD14/CD16 monocyte subsets as well as their CX3CR1 expression patterns in whole-blood measurements from 92 patients with obesity and/or OSAS with regard to plasma CXCL10 values and individual clinical parameters." (PMID 38175171, 2024). "This review provides an in-depth analysis of specific chemokines involved in the development of obesity, including C-C motif chemokine ligand 2 (CCL2), CCL3, CCL5, CCL7, C-X-C motif chemokine ligand 8 (CXCL8), CXCL9, CXCL10, CXCL14, and XCL1 (lymphotactin)." (PMID 39334887, 2024). "Relevant studies showed that CXCL10 and CXCL11 are potential predictive molecules for obesity onset and CXCL1 expression level is related to adipocyte differentiation." (PMID 37889664, 2023). "A recent study reported CXCL10 and CXCL11 as potential biomarkers for the onset of adipose tissue inflammation during obesity with CXCL11 expression correlation with NF-κB expression." (PMID 36557031, 2022). "Our results suggest that CXCL10−/− mice are protected against diet-induced NASH, in an obesity-independent manner." (PMID 27349927, 2016). "In addition to the decreased level of CD8+ T cells, obesity also induces decreased expression levels of CXCR3, CD49d, CXCL9, and CXCL10." (PMID 40863244, 2025). "Correlation analyses revealed a significant positive correlation between plasma CXCL10 and BMI within the groups of healthy donors and patients with obesity, but not with apnea–hypopnea index values of patients with OSAS." (PMID 38175171, 2024). "Research suggests that certain members of the CXCL family, particularly CXCL10 and CXCL11, could serve as potential indicators of adipose tissue inflammation in obesity." (PMID 39857642, 2024). "Data revealed significantly increased plasma CXCL10 levels in patients with obesity without OSAS compared with healthy donors (p = 0.0491), but not in normal weight patients with OSAS." (PMID 38175171, 2024). "In contrast, CXCL10 was elevated in all COVID+ patients, but was not altered by being overweight or obesity." (PMID 37361874, 2023). "In our study, we found a positive correlation between CAV1 expression and CXCLs (CXCL9, CXCL10, and CXCL11); this could be explained by the proinflammatory role and heightened presence of CXCLs in obesity." (PMID 37048092, 2023). "At the same time, the expression of chemokines (Cxcl9, Cxcl10) and the chemokine receptor CXCR3, which are key for traffic to the tumor and extravasation, were highly down-regulated in obesity, suggesting that lower chemokine levels prevented effective recruitment of immune cells to the tumor site." (PMID 35103755, 2022).
Obesity (continued). "We observed a significant induction in the levels of C3, CP enzyme, growth factor IGFBP4, and cytokine CXCL10 and interferon signaling-related genes including (IFNβ, ISG15, MX2 and OASL2), some of which have been recognized for their role either in obesity or inflammation." (PMID 33672392, 2021). "HFD-induced obesity led to upregulated expression of extracellular matrix (ECM) genes (Col3a1, Col6a3, Eln, and Sparc) and downregulated expression of immunoregulatory genes (Iigp1 and Cxcl10) in these stromal subtype cells." (PMID 32785175, 2020). "Interestingly, spontaneous (in the absence of stimulation) production of several chemokines (IL-8, CXCL10, Eotaxin, CCL4, and CCL2) was significantly reduced with pregravid obesity." (PMID 30131724, 2018). "Obesity induces macrophage infiltration into adipose tissue and dysregulated adipokine secretion, leading to persistent elevation of inflammatory cytokines such as interleukin-6 (IL-6), tumor necrosis factor-alpha (TNF-α), and C-X-C motif chemokine ligand 10 (CXCL10)." (PMID 41441521, 2025). "In a second reduced model, we eliminated all factors that did not fit the predictive model, in which, in addition to the CXCL10/CCL2 ratio (adjusted OR 15.9, p < 0.001), only the risk factors multiple gestation (adjusted OR 8.4, p = 0.006) and obesity remained (adjusted OR 6.6, p = 0.016)." (PMID 37770883, 2023). "Combined with the results that the serum CXCL10 levels were significantly elevated in overweight patients with MDD and were positively correlated with BMI in patients with MDD in the present study, these findings provide more data linking peripheral CXCL10 to the obesity status in patients with MDD." (PMID 36387880, 2022).
malaria (79 papers, 2005 to 2025). Malaria is a serious and sometimes fatal disease caused by a parasite that commonly infects a certain type of mosquito which feeds on humans. "Specifically, upregulation of CXCL10 has been linked to increased disease severity in both malaria and SCD." (PMID 39749215, 2024). "Malaria parasites have also been reported to inhibit the host’s CXCL10 synthesis in monocytes by disrupting the association of host ribosomes with CXCL10 transcripts." (PMID 36380373, 2022). "The Th1-associated chemokines CXCL9 and CXCL10 exhibited a robust increase in plasma levels during acute malaria." (PMID 33407502, 2021). "Polymorphisms in TNF-α and IL-6 genes, as well higher levels of these markers and of CXCL10 were linked to malaria clinical outcomes and pro-inflammatory activation in response to P. vivax." (PMID 34727121, 2021). "We also determined that circulating CXCL10 concentration correlated with RBC, WBC counts, and Hb in concert with the tight association between CXCL10 and malaria pathogenesis." (PMID 33424841, 2020). "Global analysis of the BAFF-var allele on total RNA expression revealed many differentially expressed genes implicated in the immune response to malaria; among them, we selected CXCL10, CR1, MIF, ICAM-1, and NFKB2 for further analysis." (PMID 33123155, 2020). "CXCL10, also known as IP-10, is majorly implicated in malaria pathogenesis, and IFN-α has recently been shown to downregulate antimalarial immunity." (PMID 30886619, 2019). "Several host and parasite indicators of malaria infection have been identified as predictors of disease prognosis (from mild uncomplicated to severe malaria) including angiopoietins, elevated CXCL10 serum levels, CXCL10 polymorphisms and free heme." (PMID 26555697, 2015). "Decreases in EPC were associated with increased heme and CXCL10 levels in addition to increased expression of TLR4 in malaria patients." (PMID 26555697, 2015). "This appears to be a feature specific of CM-susceptible mouse strains, as T cells from malaria-infected CM-resistant BALB/c animals were found to be unable to respond to CXCL10 chemotactic stimulus." (PMID 24476686, 2014). "In conclusion, the present study has provided strong evidence that the CXCL10 gene promoter −1447A>G polymorphism is a marker of susceptibility to CM in individuals living in malaria endemic areas such as India." (PMID 24349056, 2013). "Recent findings revealed that increased levels of several inflammatory chemokines including MIP-1α and MIP-1β and CXCL10 are associated with increased risk of severe malaria, suggesting a role for leukocytes trafficking in etiology of human CM." (PMID 23630573, 2013). "We assessed the correlation between polymorphisms in the CXCL10 gene promoter and clinical status of malaria patients and determined the genetic basis of CXCL10 production during P. falciparum infection in Indian patients with CM compared to non-CM patients." (PMID 24349056, 2013). "We assessed the role of the polymorphisms within the CXCL10 promoter region in differential expression of plasma CXCL10 and in promoting genetic risk factors that affect the clinical severity of malaria in the population." (PMID 24349056, 2013). "Further studies are needed in other malaria endemic populations to confirm or replicate these findings and investigate exactly how these CXCL10 promoter variants protect or render susceptibility against CM." (PMID 24349056, 2013). "Our ultimate goal is to develop novel therapies targeting Heme or CXCL10-related biological signaling molecules associated with development of fatal malaria." (PMID 22479586, 2012). "Studies conducted in our laboratory and elsewhere using human CM samples from Ghana and India revealed that excessive production of CXCL-10 in severe malaria patients is an important predictor of mortality risk in CM." (PMID 21439091, 2011).
malaria (continued). "Malaria mortality is associated with exaggerated host responses to inflammatory factors such as interferon gamma (IFNγ), tumor necrosis factor alpha (TNFα), free heme, C-X-C motif chemokine 10 (CXCL10) and parasite-derived cytotoxins." (PMID 26555697, 2015). "Since the functionality of these polymorphisms are not clearly known, the association that we have found between the CXCL10 promoter polymorphism genotypes and CM may be due to differential expression of CXCL10 affecting clinical outcomes of malaria." (PMID 24349056, 2013). "In the present study, we hypothesized that CM susceptibility in a subset of malaria patients is genetically linked to differential expression of CXCL10." (PMID 24349056, 2013). "We determined whether polymorphisms in the CXCL10 gene promoter region played a role in the clinical status of malaria patients and addressed the genetic basis of CXCL10 expression during malaria infection." (PMID 24349056, 2013). "In the present study, we hypothesized that in a subset of malaria patients, CM susceptibility is associated with variation in CXCL10 expression." (PMID 24349056, 2013). "Previous studies in both Indian and Ghanaian malaria patients demonstrated elevated CXCL10 levels in serum and cerebrospinal fluid samples and these levels were found to be associated with an increased risk of fatal Plasmodium falciparum-mediated severe malaria." (PMID 35836234, 2022). "Interestingly, recent findings revealed that increased levels of several inflammatory chemokines including MIP-1α and MIP-1β and CXCL10 or IP-10 are associated with increased risk of severe malaria, suggesting a role for leukocyte trafficking in the etiology of human disease." (PMID 23300435, 2012). "CXCL10 levels are consistently greater in malaria patients than in healthy controls, according to a recent systematic review (26 research, 1933 participants), and in the majority of investigations, higher CXCL10 levels were associated with more severe disease." (PMID 41002937, 2025). "Human circulating monocytes were identified as a major source of CXCL10 secretion in the peripheral blood of patients with malaria; in turn, however, CXCL10 has also been identified as a regulator of monocyte cytokine production." (PMID 38175171, 2024). "In vitro investigations revealed that monocytes from healthy donors secreted CXCL10 in response to the malaria pathogen, Plasmodium falciparum." (PMID 38541021, 2024). "It is also worth mentioning that neutrophils together with monocytes are the main source of CXCL10 in the spleen during murine malaria." (PMID 36839438, 2023). "Interferon gamma-induced protein 10 (CXCL10), a pro-inflammatory chemokine induced by multiple cytokines including IFNg, has been previously identified as a marker of malaria disease severity." (PMID 37465667, 2023). "Here, saliva levels of CXCL10, Ang-1, and Ang-2 previously shown to be predictive of severe malaria in malaria patients in Ghana were assessed in malaria patients." (PMID 35836234, 2022). "To date, there has been no report or study on the detection and comparative analysis of CXCL10, Angiopoietin-1 (Ang-1), and Angiopoietin-2 (Ang-2) in saliva and blood of malaria patients." (PMID 35836234, 2022). "This study provides the first evidence of elevated levels of CXCL10 and Ang-2 in the saliva of malaria patients." (PMID 35836234, 2022). "CXCL10 levels were higher in both saliva (p = 0.004) and plasma (p < 0.001) when comparing malaria patients to the non-malaria subjects." (PMID 35836234, 2022). "Among the malaria patients, there was a strong significant relationship between CXCL10 (R2 = 0.7, p < 0.0001) and Ang-1 (R2 = 0.7, p < 0.0001)." (PMID 35836234, 2022). "Although the levels of these markers in saliva were not as high as in plasma in the current study, it is noteworthy that Ang-1, Ang-2 and CXCL10 were all detectable in the saliva of malaria patients." (PMID 35836234, 2022).
malaria (continued). "Further, there was a correlation between saliva and plasma levels of Ang-1, Ang-2 and CXCL10 among malaria patients suggesting any increase or decrease in these biomarkers in plasma was also observed in saliva." (PMID 35836234, 2022). "While these studies point to CXCL10 as an attractive therapeutic target, the molecular mechanism underpinning CXCL10’s involvement in malaria is yet to be determined." (PMID 34381047, 2021). "Yet, here we show that, in the case of malaria, instead of killing the parasite, CXCL10 is adopted by the parasite as facilitator to determine when to enhance growth." (PMID 34381047, 2021). "Intriguingly, malaria patient cohort studies from endemic countries have found CXCL10 to be a highly accurate biomarker for CM disease progression." (PMID 34381047, 2021). "CXCL9 and IL-4 were the top markers when we analyzed asymptomatic malaria vs. controls, whereas IL-6 and CXCL10 were highlighted when symptomatic vs. asymptomatic malaria patients were compared." (PMID 34727121, 2021). "In the non-malaria groups, assessment of cytokine levels in uninfected Hb genotypes confirmed multiple roles of CXCL10 as a chemoattractant for monocytes and T cells and promoter of T cell adhesion to endothelial cells." (PMID 33424841, 2020). "When assessing malaria positive groups, the results indicated that CXCL10 levels were significantly elevated in HbAA+ vs HbAA- and for HbAS+ vs HbAS-." (PMID 33424841, 2020). "Among these genes, some were previously shown to play a role in severe malaria, specially CXCL10, ARG1, ATP2B4, and MMP9." (PMID 32801995, 2020). "Plasma levels of inflammatory cytokines (IFNα, IFNγ, TNF, IL-6) and chemokines (CCL2, CCL3, CCL4, CXCL10) were significantly higher during severe malaria compared to convalescence." (PMID 27792766, 2016). "We have shown that integral components of the BBB, specifically HBVEC and CD34+-HSPC, are activated to increase expression of TLR4 in addition to excess CXCL10 production in the presence of increased heme, which mimics in vivo conditions in malaria." (PMID 26555697, 2015). "Previous reports address the role of heme-induced CXCL10 in exacerbating severe malaria, and the vasculo-protective effects of HO-1’s ability to mediate CXCL10 expression." (PMID 26555697, 2015). "Heme induces production of apoptotic and inflammatory host factors, including CXCL10, and exacerbates malaria pathogenesis." (PMID 26555697, 2015). "Heme and CXCL10 concentrations in plasma obtained from malaria patients were elevated compared with non-malaria subjects." (PMID 26555697, 2015). "The expression levels of CXCL10 (5.3-fold) was highest during the early phase of malaria, while CCR3 and CCL4 were higher during febrile and recovery stages of the disease." (PMID 24188121, 2013). "In malaria, both CXCL10 and CCL2 serum protein levels increased reaching peak levels between day 4 and 7 after infection whereas CCL7 was constitutively deregulated in Ccr2-deficient animals." (PMID 23762028, 2013). "Thus, STING signaling has pleiotropic roles in malaria: in endothelium, it amplifies harmful inflammation (CXCL10-driven), while in T cells, it promotes immunoregulatory Tr1 responses." (PMID 41002937, 2025). "Moreover, peripheral blood CD14+ monocytes, in patients with symptomatic malaria, were identified as the main leucocytic sources of CXCL10." (PMID 38541021, 2024). "This study indicate that key biomarkers of malaria, Ang-1, Ang-2, and CXCL10, could be detected in saliva and may have potential application for clinical diagnosis of malaria." (PMID 35836234, 2022). "Detection of CXCL10, Ang-1 and Ang-2 in saliva may have a potential application for non-invasive malaria diagnosis." (PMID 35836234, 2022). "Furthermore, CXCL10 neutralization or genetic deletion in a malaria mice model alleviates brain intravascular inflammation and protects Plasmodium berghei ANKA-infected mice from CM13." (PMID 34381047, 2021).